MYO3A (myosin IIIA)
Description:
Actin-dependent motor protein with a protein kinase activity, playing an essential role in hearing. Probably also plays a role in vision. Required for normal cochlear hair bundle development and hearing. Plays an important role in the early steps of cochlear hair bundle morphogenesis. Influences the number and lengths of stereocilia to be produced and limits the growth of microvilli within the forming auditory hair bundles thereby contributing to the architecture of the hair bundle, including its staircase pattern. Involved in the elongation of actin in stereocilia tips by transporting the actin regulatory factor ESPN to the plus ends of actin filaments.
Synonyms: DFNA90; DFNB30
Tractability: Small molecule: a high-quality ligand is known; it belongs to a druggable protein family. PROTAC: ubiquitination databases record sites on it; a small molecule that binds it is known.
Target class: STE protein kinase group; STE protein kinase STE20 family; Enzyme; Kinase; Protein Kinase; STE protein kinase NinaC subfamily
Gene: Protein-coding gene on chromosome 10 (25,934,214 to 26,212,533, forward strand). Ensembl gene ENSG00000095777.
Subcellular location: Cytoplasm, cytoskeleton; Cytoplasm; Cell projection, filopodium tip; Cell projection, stereocilium
Subcellular location (Human Protein Atlas): Actin filaments; Cytoplasmic bodies; Plasma membrane
Pathways (Reactome):
Sensory Perception: Sensory processing of sound by inner hair cells of the cochlea; Sensory processing of sound by outer hair cells of the cochlea
Gene Ontology:
Molecular function: ADP binding; ATP hydrolysis activity; calmodulin binding; microfilament motor activity; plus-end directed microfilament motor activity; protein binding; protein kinase activity; protein serine/threonine kinase activity; ATP binding; cytoskeletal motor activity; protein serine kinase activity
Biological process: protein autophosphorylation; sensory perception of sound; cochlea morphogenesis; positive regulation of filopodium assembly; regulation of actin filament length
Cellular component: actin cytoskeleton; cytoplasm; filamentous actin; filopodium; filopodium tip; photoreceptor inner segment; stereocilium tip; cytoskeleton; myosin complex; stereocilium
Genetic constraint (gnomAD): Loss-of-function variants: 156 observed, 173.87 expected, observed/expected ratio (o/e) 0.9, 90% interval 0.79 to 1.02. The upper end of that interval is the gene's LOEUF score, 1.02, which puts it in group 4 of 6, group 1 being the genes least tolerant of losing a copy. Missense variants: 1,787 observed, 1,897.2 expected, observed/expected ratio (o/e) 0.94, 90% interval 0.9 to 0.98. Synonymous variants: 598 observed, 654.25 expected, observed/expected ratio (o/e) 0.91, 90% interval 0.85 to 0.98.
Gene-disease validity (ClinGen):
ClinGen rates the evidence that MYO3A causes each of these diseases.
nonsyndromic genetic hearing loss (autosomal recessive): Definitive.
Homologues: Orthologues: chimpanzee MYO3A (99% identical), macaque MYO3A (96% identical), dog MYO3A (87% identical), rat Myo3a (83% identical), mouse Myo3a (81% identical), rabbit MYO3A (81% identical), tropical clawed frog myo3a (62% identical), zebrafish myo3a (61% identical). Paralogues in human: MYO3B (47% identical), MYO16 (24% identical), MYO7A (22% identical), MYO7B (22% identical), MYO15A (22% identical), MYO10 (20% identical), MYO9A (20% identical), MYH9 (20% identical), MYO9B (20% identical), MYH7 (20% identical), MYH10 (20% identical), MYH11 (20% identical), and 32 more.
Diseases named in the same sentence as MYO3A in open-access papers:
MYO3A is named in the same sentence as 34 diseases in open-access papers, as found by Europe PMC text mining. Sharing a sentence is not in itself a finding about the gene and the disease. The quoted sentences say what the papers report.
deafness (20 papers, 2013 to 2025). An inherited or acquired condition characterized by the complete loss of the ability to hear from one or both ears. "Studies in model mice have also shown that loss of function of both MYO3A and MYO3B leads to profound deafness, whereas the loss of MYO3A function alone causes progressive HL similar to DFNB30, the type of HL associated with MYO3A variants in humans." (PMID 39858639, 2025). "In this study, we characterized a naturally occurring deafness-associated mutation in MYO3A to gain insight into how alterations in MYO3A motor function can impact protrusion dynamics." (PMID 38042485, 2023). "In this current study, we aimed to understand how a MYO3A deafness-associated mutation, H442N, would impact its ability to regulate actin protrusions." (PMID 38042485, 2023). "MYO3A encodes an actin-dependent motor protein and it is associated with autosomal recessive hearing impairment and deafness." (PMID 36361862, 2022). "Mutations in any of these proteins, with the exception of MYO3A/B, cause a form of deafness and blindness called Usher syndrome." (PMID 33718386, 2021). "Of the genes misregulated in Mir183/96dko homozygotes, five are known deafness genes; Myo3a, Slc26a5 and Tmc1 underlie deafness in mice and humans, while mutations in Sema3e cause deafness in people, and mice lacking Ocm exhibit progressive hearing loss." (PMID 33318051, 2020). "To investigate the mechanism of DFNB30-type deafness, we established a mouse model of Myo3a kinase domain Y137C mutation by using CRISPR/Cas9 system." (PMID 30123247, 2018). "Another important example is MYO3A for which germline mutations are associated with deafness." (PMID 39037077, 2024). "Similarly, we found that the loss-of-function deafness-associated mutation L697W reduced the motor function of MYO3A in vitro, as well as in COS7 cells." (PMID 38042485, 2023). "It is important to note that although the MYO3A L697W mutant is able to tip localize in actin based protrusions (filopodia and stereocilia), the members of the two pedigrees carrying the mutation developed deafness." (PMID 29880844, 2018). "Overall, we hypothesize that the motor properties of MYO3A are critical for its role in protrusion length maintenance, and thus deafness mutations that alter the duty ratio, force production, or actin gliding properties will specifically disrupt the length regulation function of MYO3A." (PMID 33718386, 2021). "The progressiveness of HL in this family was justified by the accumulation of the mutant MYO3A which worsened the mechanotransduction dysfunction resulting in the increase of the severity of deafness by time." (PMID 40100472, 2025). "Myo3a−/− mice have normal hearing at 1 month of age while a double knockout of Myo3a and Myo3b results in profound deafness and a dysmorphic staircase architecture of hair cell stereocilia bundles." (PMID 38562617, 2024). "Twenty-four genes were present in both normal hearing high variant load lists, including three deafness genes (POLG, GLI3, MYO3A)." (PMID 35761239, 2022). "Loss of both MYO3A and MYO3B in mice resulted in a severe deafness phenotype, as well as disrupted stereocilia structure and morphology." (PMID 33718386, 2021). "We investigated the mechanism of senile deafness in Myo3a mutant mice and examined cochlear changes." (PMID 30123247, 2018). "While these studies emphasize that loss of MYO3A function can result in protrusion dysregulation, there has been no report of a gain-of-function deafness mutation in MYO3A that increases the motor properties or protrusion dynamics." (PMID 38042485, 2023). "To determine whether Myo3a mutant mice demonstrate age-related deafness, we tested the hearing threshold of 2-, 6-, and 12-month-old Myo3a mutant and wild-type mice by ABR measurement." (PMID 30123247, 2018). "In humans, Myo3a mutation can cause nonsyndrome-type deafness." (PMID 30123247, 2018).
deafness (continued). "In addition, a role for Myo3A in cardiopulmonary disease is not consistent with its known biology, as expression of this gene is restricted to the ear and known mutations cause deafness." (PMID 24949630, 2014). "Segdups, defined as regions with > 95% homology, are features that are causally implicated in recurrent CNVs mediated by NAHR and were identified in seven deafness genes: TSPEAR (4 segdups), OTOA, STRC, MYO3A, ESPN, OTOGL, CACNA1D." (PMID 24963352, 2014). "The most frequent causative gene revealed by this technology was CDH23 (n = 3), followed by MYO15A (n = 2), MYO7A (n = 2) and other four deafness genes (PCDH15 (n = 1), USH2A (n = 1), MYO3A (n = 1) and ACTG1 (n = 1))." (PMID 25373420, 2014).
hearing loss (11 papers, 2016 to 2025). "Our findings have enabled us to predict the outcomes of hearing loss in patients with candidate MYO3A gene variants and to provide intervention in a timely manner." (PMID 39858639, 2025). "Our findings confirmed that MYO3A variants cause progressive hearing loss, with its onset varying from birth to the second decade, eventually leading to severe-to-profound hearing loss." (PMID 39858639, 2025). "Among the myosins associated with human hearing loss, MYO3A has a 30-kDa kinase domain at the N-terminus." (PMID 38562617, 2024). "In this study, we investigated the impact of a MYO3A hearing loss mutation, H442N, using both in vitro motor assays and cell biological studies." (PMID 38042485, 2023). "Mutations within the motor domain of MYO3A that disrupt its intrinsic motor properties have been associated with non-syndromic hearing loss, suggesting that the motor properties of MYO3A are critical for its function within stereocilia." (PMID 38042485, 2023). "We characterized a gain-of-function mutation in MYO3A, H442N, which is associated with hearing loss in a group of Japanese patients." (PMID 38042485, 2023). "Clinical characteristics of MYO3A-associated hearing loss patients in previous reports." (PMID 39858639, 2025). "However, this study did not elucidate any mechanism by which this mutation would affect MYO3A function and result in hearing loss." (PMID 38042485, 2023). "Mutations in MYO3A underlie a recessive form of human hearing loss, DFNB3029." (PMID 33742053, 2021). "Recently, two studies reported novel MYO3A mutations associated with non-syndromic hearing loss." (PMID 29880844, 2018). "Two genes encoding conventional myosins, MYH9 and MYH14, and four genes encoding unconventional myosins, MYO3A, MYO6, MYO7A and MYO15A, are associated with nonsyndromic hereditary hearing loss in human." (PMID 38562617, 2024). "Myosin genes are known to be responsible for 10 types of syndromic as well as non‐syndromic hearing loss (MYO7A, DFNA11/DFNB2/USH1B; MYH9, DFNA17; MYH14, DFNA4; MYO6, DFNA22/DFNB37, MYO3A, DFNB30; MYO15A, DFNB3)." (PMID 32027099, 2020). "Functional validation is recommended to be carried out in any future study for the variants detected in MYO3A, KCNQ1, PEX6, and TMC1 genes to provide stronger evidence for the pathogenicity of these variants and more robust support for their proposed role in hearing loss." (PMID 40100472, 2025). "Both MYO3A and MYO3B have been proposed to be important for regulating stereocilia elongation during development, with mutations in MYO3A that alter this function ultimately leading to non-syndromic hearing loss (DFNB30)." (PMID 38042485, 2023). "It is also possible that MYO3B could partially compensate for the effects of mutations in MYO3A and the effectiveness of this compensation could vary among individuals, explaining non-penetrance and differences in age of onset of hearing loss." (PMID 29880844, 2018).
breast carcinoma (3 papers, 2020 to 2021). "For Avalanche® only a single successful report has been published so far describing the effect of MYO3A gene knockdown on breast cancer metastasis." (PMID 32767051, 2021). "MYO3A was reported to serve as a prognostic marker for tracking progression of breast cancer toward metastasis." (PMID 34252883, 2021). "The expression of TAM-derived MIP-1β or CCL4 chemokine relates to poor survival in breast cancer patients, potentiating breast cancer cell invasion and metastasis through increased myosin IIIA (MYO3A) gene expression." (PMID 32326073, 2020).
autosomal recessive hearing loss (2 papers, 2018 to 2020). "MYO3A, encoding the myosin IIIA protein, is associated with autosomal recessive and autosomal dominant nonsyndromic hearing loss." (PMID 32519820, 2020). "Since then, several reports have identified additional MYO3A mutations associated with autosomal recessive hearing loss." (PMID 29880844, 2018). "The variant c.2090 T > G: p.Leu697Trp, [hg19]chr10:26.414.513 in the gene MYO3A (NM_017433.4) is a nonsynonymous substitution mutation, in a gene that has already been related to autosomal recessive hearing loss." (PMID 29880844, 2018).
bladder cancer (2 papers, 2023 to 2025). "A 5-gene panel was identified (NKX6-2, CA10, DBC1, MYO3A, and PENK or SOX11) and the panel had an 85% sensitivity and a 95% specificity for the detection of bladder cancer." (PMID 37627900, 2023). "Eight genes (NKX6-2, A2BP1, CA10, DBC1, MYO3A, NPTX2, PENK, and SOX11) were significantly highly methylated in the urine sediments of bladder cancer patients as compared to that of control subjects." (PMID 37627900, 2023).
bipolar disorder (1 paper, 2021). A disorder of the brain that causes unusual shifts in mood, energy, activity levels and the ability to carry out day-to-day tasks. "One example is shown within the MYO3A gene which lies upstream of GAD2, a primary regulator of GABA synthesis that has been associated with schizophrenia, bipolar disorder, and major depression." (PMID 33888138, 2021).
cardiomyopathy (1 paper, 2023). A disease of the heart muscle or myocardium proper. "Much like cardiomyopathy mutations in beta-cardiac myosin which can be gain or loss of function, mutations in MYO3A can alter motor activity in either direction, leading to changes in its ability to control protrusion length and elongation." (PMID 38042485, 2023).
cardiopulmonary disease (1 paper, 2014). "For instance, the associations between the nsSNP (rs33947968) in the Myo3A gene encompassed a clinical disease spectrum that would suggest that this nsSNP contributes to cardiopulmonary disease." (PMID 24949630, 2014).
hyperlipidemia (1 paper, 2022). "In addition, a significant increase in expression of MYO3A in hyperlipidemia (4.14), neuropathy (6.11), ketoacidosis (2.60), hypothyroidism (4.33) and PCOS (4.49) was observed." (PMID 36175575, 2022). "Analysis of upregulated DEGs has shown that the following seven genes were common between all complications of TIDM (hyperlipidemia, neuropathy, ketoacidosis, hypothyroidism and PCOS): SPINK9, TRDN, PVRL4, MYO3A, PDLIM1, KIAA1614 and GRP." (PMID 36175575, 2022).
neuroblastoma (1 paper, 2024). Neuroblastoma (NB) is the most common solid, extracranial childhood tumor. "Some potentially damaging germline variants in these two genes have been reported previously in different other cancer types including CNS tumors, neuroblastoma (MYO3A), and single cases of osteosarcomas and RMSs (MYO5B)." (PMID 39037077, 2024).
neuropathy (1 paper, 2022). A disorder affecting the nervous system that manifests with pain, tingling, numbness, and/or muscle weakness. "This further supports our present finding that expression of MYO3A was significantly increased in T1DM patients with neuropathy." (PMID 36175575, 2022).
Obesity (1 paper, 2020). Accumulation of substantial excess body fat. "MYO3A associations with interleukin-6, cortisol secretion, and BMI-adjusted waist circumference have previously been reported; in other studies, eosinophil counts and characteristics of red blood cells have been correlated with obesity or BMI, and obesity is associated with an inflammatory response." (PMID 32912333, 2020).
sarcoma (1 paper, 2024). A usually aggressive malignant neoplasm of the soft tissue or bone. "It should be noted that two patients in our cohort had somatic mutations in MYO3A and MYO3B (patients 17 and 33, respectively), further indicating a role for these genes in sarcoma." (PMID 39037077, 2024).
senile deafness (1 paper, 2018). "Our mouse model of Myo3a point mutation made by CRISPR/Cas9 technology can simulate human diseases well and provide a good mouse model for the study of senile deafness." (PMID 30123247, 2018).
triple-negative breast carcinoma (1 paper, 2015). An invasive breast carcinoma which is negative for expression of estrogen receptor (ER), progesterone receptor (PR), and human epidermal growth factor receptor 2 (HER2).
tumor (6 papers, 2021 to 2025). "In summary, the following marker genes were used for subsequent analysis in supratentorial tumours: RELA, ELL3, FBP2, PCP4L1, and MYO3A for detection of RELA+ tumours; and MRAP, IGF1, CAPS, and WWC1 for detection of YAP1+ tumours." (PMID 34314101, 2021).
cancer (5 papers, 2015 to 2024). A tumor composed of atypical neoplastic, often pleomorphic cells that invade other tissues. "The top pair of genes from the mRNA expression profile was MYO3A, a previously identified cancer gene and SWI5, a recombination repair homolog." (PMID 26138921, 2015). "In a study reporting germline PVs, among 1120 pediatric cancer patients neither MYO3A, MYO3B, or CHD1L were covered." (PMID 39037077, 2024). "Besides the well-characterised modulators of CDK1, our analysis highlights a novel potential role for MYO3A, GSK3A and GRK6 kinases, whose expression profile is highly correlated with CDK1 itself and its modulators across cancer tissues." (PMID 37898722, 2023).
MYO3A also shares sentences with these, for which no sentence is quoted: autism spectrum disorder (1 paper); cardiovascular disease (1); CNS tumors (1); diabetes (1); glaucoma (1); Hearing impairment (1); Hypercholesterolemia (1); hypothyroidism (1); Intellectual disability (1); major depression (1); microvillus inclusion disease (1); nonsyndromic hearing loss (1); osteosarcoma (1); schizophrenia (1); sensorineural hearing loss (1); soft tissue sarcoma (1); Usher syndrome (1).